SIRT4 (sirtuin 4)
Diseases named in the same sentence as SIRT4 in open-access papers (continued):
Sharing a sentence is not in itself a finding about the gene and the disease.
Hepatic steatosis (3 papers, 2011 to 2022). Steatosis is a term used to denote lipid accumulation within hepatocytes. "SIRT2, SIRT3, and SIRT4 upregulation induced by an investigational molecule also prevented the progression of hepatic steatosis and fibrosis in obese rats." (PMID 35203484, 2022). "We found that resveratrol with 4 g/kg dose partially prevented hepatic steatosis and hepatocyte ballooning and induced skeletal muscle SIRT1 and SIRT4 expression while other examined parameter were unaffected by resveratrol." (PMID 21977315, 2011).
Hyperinsulinemia (3 papers, 2017 to 2021). An increased concentration of insulin in the blood. "SIRT2 and SIRT7 have not been investigated yet, and research on SIRT4 and SIRT5 is scarce, with SIRT4 being promising against hyperinsulinemia." (PMID 33806509, 2021).
neuroblastoma (3 papers, 2020 to 2025). Neuroblastoma (NB) is the most common solid, extracranial childhood tumor. "There was a notable correlation between low SIRT4 expression and advanced stages of neuroblastoma as well as lymph node metastasis." (PMID 40710366, 2025). "Overall, the findings indicate that SIRT4 plays a critical role in neuroblastoma by acting as a tumor suppressor." (PMID 40710366, 2025). "In vitro experiments showed that SIRT4 overexpression reduced the proliferation, invasion, and migration of neuroblastoma cells significantly." (PMID 33585187, 2020). "In brief, SIRT4 exhibited a tumor-suppressor function in human neuroblastoma, and reduced the energy metabolism of tumor cells by inhibiting mitochondrial metabolism and SIRT1 expression." (PMID 33585187, 2020). "SIRT4 expression was negatively correlated with the stage (according to the International Neuroblastoma Staging System) and lymph-node metastasis." (PMID 33585187, 2020). "The duration of survival of neuroblastoma patients with low expression of SIRT4 was shortened significantly." (PMID 33585187, 2020). "This suggests that SIRT4 could be an important prognostic factor in neuroblastoma, with lower levels indicating a worse prognosis." (PMID 40710366, 2025). "Patients with higher International Neuroblastoma Staging System stages had a higher proportion of low SIRT4 expression, suggesting that SIRT4 may play a role in tumor progression." (PMID 40710366, 2025). "Similarly, in neuroblastoma, sirtuin 4 reduces tumor cell proliferation and mitochondrial energy production, suggesting its potential as a therapeutic target." (PMID 40710366, 2025). "They showed that SIRT4 expression was decreased dramatically in neuroblastoma tissues." (PMID 33585187, 2020). "Culturing U87MG and mouse neuroblastoma (Neuro-2a) cells in low-glucose medium failed to induce changes in SIRT4 and GAD1 protein and mRNA levels, ruling out the possibility that the KD drives SIRT4 overexpression solely owing to its low carbohydrate content." (PMID 38346975, 2024).
Parkinson's (3 papers, 2022 to 2023). "This is further emphasized by recent data indicating an involvement of SIRT4 in the onset and development of Parkinson's disease." (PMID 37803520, 2023). "The authors showed that MPP+ induced oxidative stress in neuronal LUHMES cells, a M. Parkinson disease model, results in the degradation of SIRT4." (PMID 37803520, 2023). "We found that SIRT4 played a role in PD models (MPTP-induced Parkinson’s mouse model and DJ-1 KO rat model) and subsequently revealed the possible mechanism of action of SIRT4 and potential molecular targets using quantitative proteomics and bioinformatics analyses in this study." (PMID 36760798, 2022).
acute pancreatitis (2 papers, 2024 to 2025). An acute inflammatory process that leads to necrosis of the pancreatic parenchyma. "While its role in the regulation of renal cell metabolism in the kidney is still poorly understood, SIRT4 deficiency in mice aggravated kidney injury in a model of acute pancreatitis, suggesting that SIRT4 may exert an important role during renal injury." (PMID 39000044, 2024).
cervical carcinoma (2 papers, 2020 to 2025). A carcinoma arising from either the exocervical squamous epithelium or the endocervical glandular epithelium. "In HeLa cervix carcinoma cells, SIRT4 showed a dynamic centrosomal localization pattern where it displayed the highest signals in centrosomal staining during G2 and early mitosis, followed by a significant drop in signal intensity from prophase onwards until late mitosis/cytokinesis." (PMID 32846968, 2020).
endometrial carcinoma (2 papers, 2021 to 2023). A malignant tumor arising from the epithelium that lines the cavity of the uterine body. "Immunohistochemical analysis in patients with endometrial carcinoma showed that the decrease of Sirt4, which was reported to inhibit glutamine metabolism, was related to the late stage of endometrial carcinoma." (PMID 37387559, 2023). "The results showed that the expression of CDK1, CALM2, and SIRT4 was significantly increased in all grades of endometrial cancer compared to the control group." (PMID 34768392, 2021).
endometrioid adenocarcinoma (2 papers, 2020 to 2021). An adenocarcinoma characterized by the presence of malignant glandular epithelial cells resembling endometrial cells. "IHC analyses were undertaken to measure expression of SIRT4 protein in 65 samples of endometrioid-adenocarcinoma tissue using microarrays." (PMID 33585187, 2020). "In addition, SIRT4 expression was lower in tissues from patients with an advanced stage of endometrioid-adenocarcinoma according to American Joint Committee on Cancer classification." (PMID 33585187, 2020). "The authors observed significantly lower SIRT4 concentration in endometrioid adenocarcinoma than in non-neoplastic tissue counterpart." (PMID 33435147, 2021). "SIRT4 expression was significantly lower in endometrioid-adenocarcinoma tissue than that in non-neoplastic tissue." (PMID 33585187, 2020).
epilepsy (2 papers, 2023 to 2024). A brain disorder characterized by episodes of abnormally increased neuronal discharge resulting in transient episodes of sensory or motor neurological dysfunction, or psychic dysfunction. "Collectively, these results suggest that the KD prevents epilepsy, which is dependent on SIRT4 function." (PMID 38346975, 2024). "The lower potency of BHB in inhibiting epilepsy in Sirt4–/– mice than in WT mice was further confirmed by video/EEG." (PMID 38346975, 2024). "PTZ-induced pronounced epilepsy symptoms in Sirt4–/– mice, as manifested by faster onset of symptoms such as limb tremors and side-to-side swaying, accompanied by longer seizures." (PMID 38346975, 2024). "The involvement of SIRT4 in the KD-mediated control of epilepsy was further investigated." (PMID 38346975, 2024). "Inactivation of GDH through SIRT4-catalyzed decarbamylation may account for the inability to relieve PTZ-induced epilepsy in Sirt4–/– mice." (PMID 38346975, 2024). "However, the GDH inhibitor EGCG potentiates BHB to inhibit epilepsy in Sirt4–/– mice." (PMID 38346975, 2024). "SIRT4 regulates GDH activity and GABA/glutamate ratio that determines neuronal excitation, it is possible that CP-K and SIRT4 can regulate glutamate and GABA homeostasis, and consequently determine GABA/glutamate ratio in epilepsy control." (PMID 38346975, 2024). "Notably, the KD failed to relieve the epilepsy symptoms in PTZ-challenged Sirt4–/– mice." (PMID 38346975, 2024).
esophageal squamous cell carcinoma (2 papers, 2020). Esophageal squamous cell carcinoma (ESCC) is a type of esophageal carcinoma (EC) that can affect any part of the esophagus, but is usually located in the upper or middle third. "Indeed Lai and coworkers showed that the Sirt4 levels in esophageal squamous cell carcinoma (ESCC) tissues from Chinese patients were higher than those in adjacent esophageal normal tissues and that the levels of the protein correlate inversely with the mean survival time of ESCC patients." (PMID 32373514, 2020).
Hyperglycemia (2 papers, 2017 to 2021). An increased concentration of glucose in the blood. "While SIRT1 enhances pancreatic beta cells response to hyperglycemia in insulin secretion, SIRT4 may blunt this response." (PMID 34899370, 2021). "Therefore, caloric restriction promotes the appropriate response of pancreatic beta cells to hyperglycemia by inhibiting SIRT4 and activating SIRT1." (PMID 34899370, 2021).
ischemia (2 papers, 2017 to 2026). A hypoperfusion of the BLOOD through an organ or tissue caused by a PATHOLOGIC CONSTRICTION or obstruction of its BLOOD VESSELS, or an absence of BLOOD CIRCULATION. "Given the parallelism between the models of neuronal death used in this work and ischemia in humans, our work suggests novel approaches targeting SIRT4 and cautions about the use of non-specific sirtuins activators or inhibitors." (PMID 28820880, 2017).
liver disease (2 papers, 2021 to 2025). "SIRT4 has been implicated in the regulation of a variety of diseases, including liver disease, through the regulation of ferroptosis." (PMID 40765819, 2025). "Although SIRT4 is involved in the pathophysiological processes of liver diseases, its role in LIRI remains unknown." (PMID 40765819, 2025). "Notably, SIRT4 is involved in the regulation of liver disease." (PMID 40765819, 2025).
lymph node metastasis (2 papers, 2016 to 2020). "In final part of present study, we observed a strong association between SIRT3, SIRT4, MTUS1 and OGG1-2a gene expression and lymph node metastasis." (PMID 26785117, 2016). "SIRT4 expression was negatively correlated with INSS and lymph node metastasis." (PMID 33585187, 2020). "Also, there was a negative correlation between expression of SIRT4 and Drp1 in primary NSCLC tissues and lymph-node metastatic tumors." (PMID 33585187, 2020).
multiple sclerosis (2 papers, 2014 to 2021). A progressive autoimmune disorder affecting the central nervous system resulting in demyelination. "Genetic variability in HDAC9, along with variants in HDAC11, SIRT4 and SIRT5, has also been shown to influence brain volume in multiple sclerosis (MS) patients, as assessed used neuroimaging methods." (PMID 25322459, 2014). "As with the SIRT4 and SIRT5 genes, variants in HDAC11 were also shown to influence multiple sclerosis in terms of brain volume." (PMID 25322459, 2014).
psoriasis (2 papers, 2021 to 2023). An autoimmune condition characterized by red, well-delineated plaques with silvery scales that are usually on the extensor surfaces and scalp. "There is a significant reduction in the expression of SIRT1, SIRT2, SIRT3, SIRT4 and SIRT5 and an increase in the expression of SIRT6 and SIRT7 in psoriasis." (PMID 37445960, 2023). "The dysregulation of this auto-regulatory loop could be also due to the abnormal expression of SIRTs in psoriasis, with the downregulation of SIRT1, SIRT2, SIRT3, SIRT4, and SIRT5 and upregulation of SIRT6 and SIRT7 in skin lesions skin, as previously reported." (PMID 34202251, 2021).
viral infection (2 papers, 2021). "We believe that the interaction of HBx and SIRT4 during viral infection (HBV infection in this case) and their roles on carcinogenesis deserve further studies, which may provide insights for the development of therapeutics against HBV-induced HCC." (PMID 33931611, 2021). "SIRT3, SIRT4, and SIRT5 are mitochondrial deacetylases regulating a wide range of metabolic pathways that are known to be altered during viral infection as confirmed in our study." (PMID 34149631, 2021).
adenoma (1 paper, 2020). A neoplasm arising from the epithelium. "They found that the proportion of patients with high expression of SIRT4 in normal tissues (61.1%) was greater than that for patients with adenomas (52.6%) or CRC (52.5%)." (PMID 33585187, 2020). "Also, 41% (7/17) of these lung tumors were adenomas and 59% (10/17) were carcinomas, from SIRT4-KO mice." (PMID 33585187, 2020).
age (1 paper, 2024). A temporal measurement of the time period elapsed since an identifiable point in the life cycle of an organism. "Although SIRT4 may play a protective role in some specific cellular contexts, SIRT4 is proposed to promote mitochondrial fusion, which is one of the hallmarks of age-related deterioration of the mitochondria, by directly interacting with OPA1." (PMID 39683482, 2024).
age-related macular degeneration (1 paper, 2022). Age-related loss of vision in the central portion of the retina (macula), secondary to retinal degeneration. "Upregulation of SIRT4 expression may be a new direction for the treatment of retinal neuronal degeneration caused by glaucoma and age-related macular degeneration." (PMID 35185463, 2022).
alcoholic fatty liver disease (1 paper, 2022). Lipid infiltration of the hepatic parenchymal cells that is due to alcohol abuse. "Sirtuin 1 (SIRT1), the SIRT1/NF-κB axis, SIRT3, and SIRT4 play a major role in regulating hepatic lipid metabolism, controlling oxidative stress, and mediating chronic inflammation in NAFLD and alcoholic fatty liver disease." (PMID 35203484, 2022).
Alzheimer disease (1 paper, 2026). A progressive, neurodegenerative disease characterized by loss of function and death of nerve cells in several areas of the brain leading to loss of cognitive function such as memory and language. "For instance, STAT2 regulates Sirt4 transcription and activates the mTOR pathway, thereby promoting neuronal apoptosis in Alzheimer’s disease." (PMID 41523985, 2026).
bladder urothelial cancer (1 paper, 2020). "The same analysis was also performed in a TCGA bladder urothelial cancer cohort and a similar SIRTs expression profile was found, with IHG showing significantly increased SIRT4 expression levels comparing to PLG, whereas SIRT5 and SIRT6 expression levels were decreased." (PMID 32344886, 2020).
Cerebral ischemia (1 paper, 2017). Restriction of arterial blood supply to the brain associated with insufficient oxygenation to support the metabolic requirements of the tissue. "In this work, we investigated the role of Caenorhabditis elegans mitochondrial sirtuin SIR-2.3, homologous to mammalian SIRT4, in two distinct models of neuronal death with morphological and molecular features of necrosis that occurs in cerebral ischemia." (PMID 28820880, 2017).
chronic kidney disease (1 paper, 2024). Impairment of the renal function secondary to chronic kidney damage persisting for three or more months. "Consistently, elevated nuclear accumulation of SIRT4 was observed in kidney sections from patients with chronic kidney disease (CKD) with severe collagen deposition." (PMID 39495216, 2024).
clear cell adenocarcinoma (1 paper, 2019). A malignant neoplasm composed of glandular epithelial clear cells. "In Hendrix’s dataset, SIRT1, SIRT3, and SIRT4 expression levels were significantly lower in serous, endometrioid, mucinous, and clear cell adenocarcinoma than they were in normal ovarian tissues." (PMID 31572453, 2019).
diabetic cardiomyopathy (1 paper, 2025). Diabetic cardiomyopathy is a disorder of the heart muscle in people with diabetes. "Considering that the roles of SIRT3 and SIRT5 in diabetic cardiomyopathy have been validated 23, 28, we assessed the expression patterns of SIRT2 and SIRT4 in heart tissues." (PMID 39781464, 2025).
gastric adenocarcinoma (1 paper, 2022). "SIRT4 expression in gastric adenocarcinoma was substantially lower than that in healthy tissue." (PMID 36499440, 2022).
gestational diabetes (1 paper, 2020). Carbohydrate intolerance first diagnosed during pregnancy. "In a previous study, we observed decreased SIRT1 and SIRT4 transcript levels in fetal endothelial cells and HUVECs from pregnancies complicated by gestational diabetes, where a hypoxic component can also be postulated." (PMID 32796661, 2020).
glaucoma (1 paper, 2022). Increased pressure in the eyeball due to obstruction of the outflow of aqueous humor. "Considering that excitotoxicity caused by glutamate is an important part of glaucoma injury, investigating the role of SIRT4 in glutamate-glutamine metabolism is of great significance." (PMID 35185463, 2022).
glutamine metabolism disorder (1 paper, 2020). "Given the negative regulation of SIRT4 on SIRT1 and the intricate relationship between AMPK and SIRT1, we hypothesized that glutamine metabolism disorder might be involved in SIRT4-induced SIRT1 inhibition." (PMID 32863939, 2020).
head and neck cancer (1 paper, 2016). A primary or metastatic malignant neoplasm affecting the head and neck. "The present study was designed to study the expression pattern of selected mitochondrial tumor suppressor genes in head and neck cancer and to investigate the association of SIRT 3, SIRT4 and MTUS1 gene expression with the clinical characteristics and prognosis of head cancer patients." (PMID 26785117, 2016). "However, the implications of mitochondrial tumor suppressor genes SIRT3, SIRT4 and MTUS1 in head and neck cancer are largely unknown." (PMID 26785117, 2016).
hearing loss (1 paper, 2024). "SIRT4, SIRT5, and SIRT6 lacked any evidence of involvement in hearing loss, but their expressions were slightly altered in an ARHL model of mice in various tissue types of an ARHL model of mice." (PMID 39204103, 2024).
Hyperammonemia (1 paper, 2020). An increased concentration of ammonia in the blood. "We employed HeLa-SIRT4-eGFP cells, a stable cell line overexpressing SIRT4, and the corresponding control cells (HeLa-eGFP) to test whether inhibition of mitochondrial GDH by SIRT4 can also restore mitochondrial respiration and/or mitochondrial morphology upon hyperammonemia." (PMID 32917661, 2020).
insomnia (1 paper, 2023). A sleep disorder characterized by difficulty in falling asleep and/or remaining asleep. "Warming Yang Strategy improve neurological recovery in insomnia rats through SIRT4 by inhibiting inflammation and apoptosis." (PMID 37647454, 2023). "Morris water maze was applied to investigate the influence of WY and SIRT4 on the neurological recovery of insomnia rats." (PMID 37647454, 2023). "Open‐field test was also used to study the influence of WY and SIRT4 on the neurological recovery of insomnia rats." (PMID 37647454, 2023). "WY improve neurological recovery in the insomnia rats through SIRT4 by inhibiting inflammation and apoptosis." (PMID 37647454, 2023). "This research might provide a novel insight for the prevention and treatment of insomnia through targeting SIRT4." (PMID 37647454, 2023). "As a functionally similar factor in the same family, SIRT4 has a high probability of also being located in key nuclei, playing a regulatory role in inhibiting neuroinflammatory responses and corresponding neuronal apoptosis, as well as in combating insomnia." (PMID 37647454, 2023). "This study might provide a new therapeutic strategy for the treatment of insomnia through targeting SIRT4." (PMID 37647454, 2023). "This study might provide a new insight for the treatment of insomnia through targeting SIRT4." (PMID 37647454, 2023). "We demonstrated that WY might improve the neurological recovery of insomnia rats through SIRT4." (PMID 37647454, 2023). "However, if WY could improve neurological recovery in the insomnia rats through targeting SIRT4 has not been reported." (PMID 37647454, 2023).
kidney damage (1 paper, 2022). "SIRT4 also plays a role in the regulation of mitochondrial function and the pathogenesis of metabolic disorders including renal dysfunction, but its exact role in diabetic-induced kidney damage remains unclear." (PMID 35956936, 2022).